Y_RNA (Y RNA )
Gene: Miscellaneous RNA gene on chromosome 22 (36,440,880 to 36,440,970, reverse strand). Ensembl gene ENSG00000252225.
Homologues: Orthologues: chimpanzee Y_RNA (99% identical). Paralogues in human: RNY4P3 (80% identical), Y_RNA (79% identical), RNY4P10 (78% identical), RNY4P13 (78% identical), RNY4P7 (78% identical), RNY4 (77% identical), Y_RNA (77% identical), RNY4P19 (76% identical), RNY4P24 (76% identical), RNY4P36 (76% identical), RNY4P37 (76% identical), RNY4P6 (76% identical), and 89 more.